TNF (tumor necrosis factor)
Diseases named in the same sentence as TNF in open-access papers (continued):
Sharing a sentence is not in itself a finding about the gene and the disease.
Cachexia (continued). "Fourth, young blood’s components may instead exacerbate the progression of the disease, such as high levels of GDF11 cause severe cachexia, death, cardiac and skeletal muscle wasting, TNF-α and IL-6 promote cardiac remodeling and inflammation generation." (PMID 40969375, 2025). "Their contrasting viewpoint hinged on the hypothesis that curcumin works via blocking TNF alpha, a cytokine known for exacerbating symptoms of cachexia including weight loss." (PMID 40759997, 2025). "TNF‐α has been implicated as a possible mediator of muscle catabolism via stimulation of the ubiquitin‐proteasome system and plays a role in the induction of cachexia in animal studies." (PMID 40641155, 2025). "Cancer cachexia is associated with systemic inflammation, and some proinflammatory cytokines were found to induce muscle atrophy and lipolysis in cachexia, including IL-6 and TNF-α." (PMID 39519503, 2024). "Several inflammatory cytokines, including TNF-α, are associated with cachexia and anorexia." (PMID 38515869, 2024). "Additionally, pro-inflammatory cytokines (especially IL-1, IL-6, and TNF-α) were shown to be important factors in the development of cachexia, a hypercatabolic state associated with muscle and adipose tissue wasting." (PMID 37630845, 2023). "In addition, increased levels of TNF-α, IL-1, IL-8, and IL-10 in patients with cancer cachexia result in increased energy expenditure, loss of appetite, and muscle atrophy." (PMID 37217930, 2023). "However, as an endogenous pyrogen that causes fever, chronic exposure to a low dose of TNF can cause cachexia, wasting syndrome, and depression." (PMID 36593850, 2022). "Chronic inflammation caused by cachexia may induce the continuous activation of the brain–fat axis through hypothalamic TNF signals, leading to the progressive lipolysis of cachexia." (PMID 36105371, 2022). "TNF-α is an acute phase reactant mainly released by activated macrophages as well as by a number of other immune cells that have been associated with the development of cachexia in the setting of cancer and infectious diseases." (PMID 35743911, 2022). "A systematic review also suggested a network of cytokines (interleukin [IL]-6, tumor necrosis factor-alpha [TNFα], and IL-8) that may be associated with cachexia development." (PMID 36465353, 2022). "Many rodent tumors causing in vivo cachexia synthesize and secrete TNFα." (PMID 36078078, 2022). "Indeed, increased circulating levels of inflammatory cytokines (e.g., interleukin-6 (IL-6), tumor necrosis factor alpha (TNF-α) and C-reactive protein) and innate immune cells (e.g., neutrophils) are all associated with cachexia in humans." (PMID 34439145, 2021). "Besides, the CC genotype carriers had a 9.7- to 13.2-fold higher risk of cachexia with the highest level of plasma TNF-α that directly reflects the alternation in patients’ nutritional status due to the underlying inflammatory response." (PMID 34900737, 2021). "Cancer-associated cachexia is promoted by chronic inflammation mediated through several proinflammatory cytokines, including interleukin-1 (IL-1), IL-6, and tumor necrosis factor alpha (TNF-α)." (PMID 34421889, 2021). "The concept of a causal role of pro-inflammatory cytokines mediating cachexia in humans has only been addressed very limitedly and only in a few pathological conditions, using targeted therapeutics that deplete specific cytokines such as TNF-α and IL-6." (PMID 33329046, 2020). "In addition, implantation of a continuously TNF-α producing tumor cell line into mice, elicited cachexia and weight loss, with reduced food intake, compared to the control, non-secreting tumor cell line." (PMID 33329046, 2020). "However, TNF-α and IL-6 levels remained increased in the serum of these animals, highlighting a possible indirect action of these cytokines in driving cachexia and adipose tissue loss through lipolytic mechanisms." (PMID 33329046, 2020).
Cachexia (continued). "Finally, in a model of cachexia induced by Trypanosoma cruzi, mice treated with anti-TNF-α antibodies displayed significant attenuation of weight loss, while anti-IL-6 and anti-IFN-γ antibodies had no such effect." (PMID 33329046, 2020). "TNFα, also known as cachectin, is the first inflammatory cytokine linked to cancer cachexia due to its elevation in the circulation of cancer patients with cachexia, and its capacity to induce muscle wasting in laboratory animals." (PMID 31480237, 2019). "Indeed, NF-κB mediates MyoD down-regulation induced by TNFα and interferon-γ, thereby contributes to skeletal muscle loss in cachexia by inhibiting muscle regeneration." (PMID 31480237, 2019). "Furthermore, poor-performance status and cachexia, associated with cytokines of IL-6 and TNF, are well known." (PMID 31426531, 2019). "On the other hand, TNF-α was also recognized as a significant regulator of both inflammatory and autoimmune diseases and, moreover, it was implicated in inflammatory-associated tumors and the development of cachexia." (PMID 29802455, 2018). "Notably, the cachexia-associated, pro-inflammatory TNF was upregulated 2.9-fold after weight loss, while expression of all interleukins (IL1B, IL6, IL10), as well as CCL3 was much lower than in the lean group." (PMID 27900559, 2017). "In addition, inflammatory response is associated with increased circulating levels of specific cytokines, such as IL-1, IL-6, IFNγ, TNFα, and acute-phase proteins that lead to hypermetabolism and weight loss in patients with anorexia and cachexia." (PMID 26504362, 2015). "However, the elevated expression of certain inflammatory cytokines such as TNFα, which is often associated with cachexia and weight loss, require further exploration in the IfitmDel mice." (PMID 25856311, 2015). "Here, we examined levels of typical serological factors, such as IL-6, TNF-α, and leptin, and used metabolomics to identify metabolites associated with cachexia in patients with pancreatic cancer and investigate intra-day variations in levels of these metabolites." (PMID 25411961, 2014). "Furthermore, TNFα is associated with cachexia in Trypanosoma cruzi infection and during schistosomiasis." (PMID 23349631, 2013). "TNF-α is associated with anorexia in wasting syndromes (Beutler and Cerami 1986 ▶)." (PMID 25050262, 2013). "Cytokines, including Tumor Necrosis Factor (TNF)/cachectin, interleukin (IL)-1α, IL-1β, interferon-γ, and IL-6 have been implicated in cachexia both through experimental manipulation in mouse models and by association of serum levels in patients with cachexia." (PMID 21799891, 2011). "However, TNAP3-deficient mice develop severe inflammation and cachexia, are hypersensitive to both lipopolysaccharide and TNF, and die prematurely, consistent with failure to terminate TNF-induced NFκB responses." (PMID 19007433, 2008). "The effect of the synthetic progesterone, megestrol acetate, on weight loss induced by both tumour necrosis factor alpha (TNF) as a model for the cachexia accompanying the acquired immunodeficiency syndrome and by a cachexia-inducing tumour (MAC16) has been studied in NMRI mice." (PMID 2206950, 1990). "Notably, serum levels of TNF-α and IL-6, the pro-inflammatory cytokines most commonly implicated in cancer cachexia did not correlate with the degree of weight loss or predict the occurrence of cachexia at the diagnosis of PC in this study." (PMID 37280516, 2023). "They showed that, TNF-α polymorphism (rs1799964; −1031 T/C) and plasma level of this cytokine may be related to the occurrence of cachexia (defined on the basis of SGA: patients classified as SGA-B were considered as pre-cachectic, whereas patients classified as SGA-C were considered as cachectic)." (PMID 35884467, 2022).
Cachexia (continued). "Adipose tissue is an important endocrine organ that releases a variety of factors which include cytokines (TNF-α, IL-6, IL-1β, IL-10, among many others) and adipokines which promote important systemic inflammation and are possibly associated with the pathogenesis of cachexia and cardiac cachexia." (PMID 35326490, 2022). "However, it has become obvious from many investigations that TNF’s activity can only be understood in the presence of other cytokines, some of which have activities that are at least as important as TNF-α in causing cachexia." (PMID 35159388, 2022). "A high level of TNFα production was speculated to be the cause of cachexia in the other study." (PMID 34485171, 2021). "However, TNFα can also cause cachexia that may explain the decrease in the body fat of rodents treated with IL-15." (PMID 27684068, 2016). "Therefore, higher production of TNF-α in cancer-associated cachexia may lead to the altered differentiation status of adipocytes." (PMID 25415607, 2014). "Interestingly, TNFα is associated with cachexia in parasite infections." (PMID 23349631, 2013). "Indeed, TNFα was significantly increased in the serum of infected mice at the time of secondary hypophagia, comparable to levels known to directly cause cachexia in mouse infection models." (PMID 23349631, 2013). "Tumor Necrosis Factor α (TNFα) is a well-known example of this dual role, as it was originally named ‘cachectin’ due to its proinflammatory effects which are also associated with metabolic effects such as cachexia, weight loss, tissue fatty acid release and insulin resistance." (PMID 23667486, 2013). "However, TNF-α is a pleiotropic cytokine contributing to both protective immunity and pathologic responses depending upon concentration and duration of production (e.g. TB reactivation occurs after TNF-α blockade, while cachexia or extreme wasting is caused by chronic excessive TNF-α production)." (PMID 23326234, 2013). "TNF-α influences the development of cachexia through multiple mechanisms, including lipid metabolism, protein homeostasis, and neural regulation." (PMID 41526343, 2026). "TNF-α level is elevated in the sputum of COPD patients and serum of severe COPD patients with cachexia and skeletal muscle loss." (PMID 41599784, 2026). "The authors further demonstrated that CD4+ T helper cells are the primary source of cachexia-related proinflammatory cytokines such as TNF-α." (PMID 41526343, 2026). "Tumor necrosis factor-alpha (TNF-α) is a pro-inflammatory cytokine capable of inducing cachexia in murine models." (PMID 40519290, 2025). "Recently, OC was reported to protect C2C12 myotubes against the reduction in size deriving from exposure to TNF-α or to the medium conditioned by cultured C26 cells (CM-C26), a tumour well known to induce cachexia in the host mice." (PMID 40732959, 2025). "The role of IFNγ in cachexia is also not fully understood; however, it has been shown to synergize with TNF‐α to promote muscle wasting." (PMID 39764565, 2025). "Proinflammatory cytokines such as IL-6, IL-1β, TNF-α, and IFN-γ are associated with muscle wasting in both clinical and preclinical cancer cachexia." (PMID 40469669, 2025). "Cytokines like TNFα, IFNγ, IL-1, and IL-6 are major promoters of the acute phase response, which increases muscle catabolism and resting energy expenditure, fostering cachexia." (PMID 40362192, 2025). "Ghrelin also acts via GH-independent pathways to suppress the pro-inflammatory and catabolic milieu that drives cachexia as it stimulates the release of the anti-inflammatory cytokine IL-10 while reducing levels of TNF-α, IL-1β, and IL-6." (PMID 40869331, 2025).
Cachexia (continued). "Gene set enrichment analysis (GSEA) showed that in cachexia, TNF‐α, inflammatory and JAK‐STAT3 pathways were upregulated, and myogenesis pathways were downregulated." (PMID 41305932, 2025). "An important contribution to the development of cachexia is made by pro-inflammatory cytokines such as TNF-α, IL-6, LIF and IFN-γ, produced by both the host and the tumour." (PMID 40732959, 2025). "In contrast, in cachexia, increased lipolysis is driven primarily by tumour-derived factors (e.g., IL-6, TNF-α, and PTHrP) and systemic inflammation, leading to a net loss of fat mass rather than fat accumulation (Joshi & Patel 2022)." (PMID 41373779, 2025). "For instance, tumor-derived sEVs enriched in miR-21 have been shown to activate Toll-like receptors 7 and 8 (TLR7/8), inducing proinflammatory cytokines such as IL-6 and TNF-α, and promoting cachexia in murine cancer models." (PMID 40806377, 2025). "Taken together, these results suggest that, according to previous findings, IL6 is the main driver of muscle atrophy in the experimental model of C26‐induced cachexia, whereas TNFα and myostatin only have marginal roles." (PMID 40448398, 2025). "In support of this idea, several mice models of cachexia demonstrate an increased content of hypothalamic TNFα and IL1, S31." (PMID 39962362, 2025). "GDF-15 and TNF-α perform better at cachexia classification than other commonly used classifiers of cachexia." (PMID 39989973, 2025). "It has been reported that malignant tumours release cytokines into the circulation, especially TNFα, which can induce cachexia systemically." (PMID 39971710, 2025). "In the mouse model of male C57BL/6J mice that were injected with Lewis Lung Carcinoma cells, inflammatory molecules such as TNFα and IL-6 showed a crucial role in triggering various secondary symptoms that affected nutrition and mental wellbeing in cachexia." (PMID 40362192, 2025). "Sophocarpine and Matrine, which inhibit TNF-α and IL-6 production, reduced cachexia symptoms in animal models." (PMID 40519290, 2025). "In the early 2000s, two pathways for cachexia were underscored, characterized by a decrease in transcription of myosin heavy chain originating from TNF-a or by an increase in ubiquitination of myosin attributed to IL-6." (PMID 38473431, 2024). "The mRNA was isolated from mouse kidneys and was used to examine the expression levels of signaling proteins, inflammatory cytokines, and genes responsible for inducing cachexia (IL-1β, IL-6, TNF-α, TGF-β, GDF-15, and MYD88)." (PMID 39394174, 2024). "TNF-α can stimulate angiogenesis and osteoclastic bone resorption and can contribute to cachexia and anemia." (PMID 39339184, 2024). "Since systemic inflammation is recognized as another feature of both experimental and clinical cachexia, the serum levels of interleukin 6 (IL-6) and tumour necrosis factor α (TNF-α) were measured." (PMID 39327432, 2024). "The pathogenesis of cachexia is a multifactorial process mediated predominantly by proinflammatory cytokines under NF-κB control such as TNF-α, IL-1, IL-6, interferon-γ, and leukemia inhibitory factor." (PMID 39114348, 2024). "The results showed a sustained increase in levels of the mRNA expression of TNFα, IL-1β, and IL-6 in hypothalamic microglia, which started from the pre-cachexia stage and lasted for the cachexia stage after pancreatic cancer cell transplantation." (PMID 38685046, 2024). "This study is the first to describe that OC modulates alterations induced in C2C12 myotubes by stimuli known to induce muscle wasting in vivo, namely TNF-α, or in the medium conditioned by the C26 cachexia-inducing tumor (CM-C26)." (PMID 38732549, 2024). "Plasma levels from head and neck cancer patients with and without cachexia showed a decrease in miR-130a levels with an increase in TNF-α levels that was highly specific to individuals with cachexia, demonstrating potential as a cancer cachexia biomarker." (PMID 38254849, 2024).
Cachexia (continued). "Pro-inflammatory cytokines secreted by these cells include tumor necrosis factor (TNF)-α, interleukin (IL)-6, and IL-1β, and many studies have focused on the characteristics of cachexia induced by these factors." (PMID 38273418, 2024). "Noteworthy, the reduction in myotubes diameter by Ser/Gly depletion was comparable to that observed following 48 h of treatment with the cachexia inducer factor TNF-α." (PMID 39706853, 2024). "In a phase II clinical trial evaluating the efficacy and safety of celecoxib in advanced cancer patients with cachexia, the body weight and tumor necrosis factor (TNF-α) levels improved following celecoxib treatment." (PMID 37711747, 2023). "Systemic inflammation is one of the important characteristics of cancer cachexia, and inflammatory cytokines IL-1β, IL-6, and TNF-α in the serum of cancer cachexia patients have been confirmed." (PMID 37190306, 2023). "Inflammatory cytokines such as IL-1, IL-6, TNF-α, and IFN-γ were commonly identified and associated with the development of cachexia." (PMID 36831513, 2023). "Proinflammatory cytokines, particularly TNF-α, IL-6, and IL-1β, are considered to be important mediators of cachexia induction." (PMID 37446099, 2023). "Regular exercise lowered TNFα release from immune cells and suppressed TNFα in the hypothalamus of rats affected by cancer-induced cachexia." (PMID 36829858, 2023). "In C-26-induced cancer cachexia mice, pre-administration of adalimumab (a TNF-α inhibitor) significantly reduced cancer cachexia, as evidenced by significantly reduced weight loss, and leg muscle retention." (PMID 37533569, 2023). "Increased production of cytokines, such as IFNγ, TNF-α, and IL-6, is a common feature of muscle wasting and cachexia." (PMID 37217930, 2023). "A literature review highlights the significant role of pro-inflammatory cytokines, such as TNF-α, IL-6, and IL-1, and certain chemokines, like CXCL8/IL-8, as procachectic agents produced by different TME cell types in CRC-associated cachexia." (PMID 37629689, 2023). "Several studies have demonstrated that chemotherapy-induced cachexia or CRF is associated with an increase in proinflammatory cytokines, such as TNF-α, IL-6, and IL-1β." (PMID 37699022, 2023). "As cachexia (with extreme weight loss and muscle wasting) is a hallmark of AIDS and TI-IFNs are known to induce TNF-α/cachectin, we assessed the impact of IFN-α blockade on body weight." (PMID 35104248, 2022). "The main drivers of cachexia are cytokines such as interleukin-6 (IL-6), tumor necrosis factor-alpha (TNF-α), macrophage inhibitory cytokine 1 (MIC-1/GDF15) and transforming growth factor-beta (TGF-β)." (PMID 36078078, 2022). "Increased levels of pro-cachectic cytokines, such as interleukin (IL)-1, IL-1α, IL-6 and tumor necrosis factor-α (TNF-α) are associated with weight loss, skeletal muscle catabolism and apoptosis in cancer cachexia." (PMID 35204066, 2022). "Another trial analysing the effectiveness of OHR/AVR118, an agent targeting both IL‐6 and TNF‐α, indicated that cancer patients with cachexia patients improved anorexia, strength, and dyspepsia." (PMID 35080147, 2022). "Previous studies have identified several cachexia-related cytokines, including interleukin-6 (IL-6), tumor necrosis factor alpha (TNF-α), IL-1β, and the leukemia inhibitory factor (LIF)." (PMID 35740622, 2022). "In the early stage of cachexia, serum TNF is positively correlated with serum free fatty acid (FFA)." (PMID 36081564, 2022). "The available literature highlights the role of TNF‐α as a key mediator of cachexia given the cytokine's ability to activate nuclear factor‐κB, one of the main pathways that determine skeletal muscle atrophy." (PMID 35080147, 2022). "In cachexia-induced catabolic processes, many different factors are involved, including inflammatory molecules (TNF-α, INF-γ, IL-6, IL-1β), hormones (cortisol, glucagon), and oxidative stress." (PMID 36364788, 2022).